RFC3 (replication factor C subunit 3)
Diseases named in the same sentence as RFC3 in open-access papers (continued):
Sharing a sentence is not in itself a finding about the gene and the disease.
tumor (15 papers, 2009 to 2025). "Survival analysis indicates that the aberrant expression of RFC3 is significantly associated with various survival outcomes across a range of tumor types." (PMID 40980067, 2025). "Gene Set Enrichment Analysis (GSEA) was employed to identify tumor signaling pathways associated with RFC3." (PMID 40980067, 2025). "High RFC3 expression was closely associated with poor prognosis, adverse clinical features, and adverse tumor microenvironment characteristics in DLBCL patients." (PMID 40980067, 2025). "RFC3 is involved in key oncogenic pathways and contributes to an immunosuppressive tumor microenvironment, underscoring its dual potential as both a diagnostic marker and a therapeutic target in various tumours." (PMID 40980067, 2025). "Further investigation using both in vitro and in vivo models is essential to elucidate the molecular pathways through which RFC3 influences tumor biology and the tumor immune microenvironment." (PMID 40980067, 2025). "In our results, RFC3 expression is insignificant in typical vs. tumor of CRC patients but the results are inconsistent with overall survival data of CRC patients." (PMID 38504096, 2024). "Additionally, direct functional validation of RFC3′s involvement in tumor progression and immune regulation remains limited, with few experimental studies addressing these mechanisms." (PMID 40980067, 2025). "The pan-cancer analysis also revealed elevated RFC3 expression across several tumor types." (PMID 40980067, 2025). "Furthermore,RFC3 gene expression was one of the most differentially expressedbetween normal and tumor tissue." (PMID 26678268, 2015). "Additionally, pan-cancer analysis indicated that RFC3 is overexpressed across multiple tumor types." (PMID 40980067, 2025). "In summary, RAD51, TIMELESS, RFC3, and TONSL converge on pro-proliferative pathways that sustain tumor survival and expansion." (PMID 41179682, 2025). "Intersection of these gene sets yielded four high-confidence tumor dependency genes (TONSL, TIMELESS, RFC3, RAD51) for further investigation." (PMID 41179682, 2025). "The RFC family consists of five protein subunits, RFC1, RFC2, RFC3, RFC4, and RFC512; which are strongly connected with tumor growth and metastasis." (PMID 38504096, 2024). "The expression of replication factor C complex (RFC2, RFC3 and RFC4) is indicative of proliferative potential (high cell division rates) of BRCA1 tumours." (PMID 25521701, 2014). "RFC3 is overexpressed in colorectal cancer (CRC), promotes tumor growth by binding to KIF14." (PMID 40980067, 2025). "Overall, our study identifies TONSL, TIMELESS, RFC3, and RAD51 as tumor dependency genes." (PMID 41179682, 2025). "Notably, TONSL, TIMELESS, RFC3, and RAD51 exhibited significantly higher expression levels within the tumor regions compared to the tumor stromal areas, suggesting their predominant role in tumor cells." (PMID 41179682, 2025). "Furthermore, expression inhibition of TMPO, TOP2A, RFC3, GINS1, and CKS2 genes could prevent tumor growth." (PMID 34249670, 2021). "In addition, expression inhibition of TMPO, TOP2A, RFC3, GINS1, and CKS2 genes could prevent tumor growth and TRIB3 expression suppression would be a favorable target for anti−angiogenic therapy." (PMID 34249670, 2021). "However, the expression levels of RFC1, RFC2, RFC3, and RFC4 did not exhibit significant differences in various tumor stages." (PMID 38504096, 2024).
cancer (9 papers, 2015 to 2025). A tumor composed of atypical neoplastic, often pleomorphic cells that invade other tissues. "Moreover, in ACC, BRCA, CESC, COAD, and other cancers, elevated RFC3 expression is associated with an unfavorable DFI." (PMID 40980067, 2025). "Our findings indicate that these pathways play vital roles in cancer progression, highlighting the essential function of RFC3 in sustaining the malignant phenotype of DLBCL." (PMID 40980067, 2025). "Dysregulation of replication factor C subunit 3 (RFC3) gene expression were associated with disease progression and poor prognosis in various cancer types." (PMID 40980067, 2025). "Although upregulation of RFC3 has been reported in several cancers, a correlation between RFC3 expression and progression of ER-positive breast cancer has not been reported." (PMID 38059884, 2023). "As the dominant gene in the 13q13 amplicon, RFC3 is considered to be an oncogene or anti-oncogene in different cancers based on its cellular and histological characteristics." (PMID 35483337, 2022). "Multiple studies indicated RFC3 was overexpressed and correlated to the progression of human cancers." (PMID 31850052, 2019). "Additionally, the expression of RFC3 exhibits a positive correlation with TMB across various cancer types, including BLCA, KICH, LGG, LUAD, PRAD, and UCEC." (PMID 40980067, 2025). "Replication factor C subunit 3 (RFC3), another subunit within the RFC complex, plays a crucial role in DNA replication and repair processes and has been associated with various types of cancer." (PMID 40980067, 2025). "In summary, this means that RFC3 may act as an oncogene in cancers." (PMID 35483337, 2022).
infection (2 papers, 2020 to 2025). The state of being infected such as from the introduction of a foreign agent such as serum, vaccine, antigenic substance or organism. "Recent studies have shown that upon infection with ZIKV, FAM111A is activated by IRF2, which enhances replication factor C subunit 3 (RFC3) signaling and inhibits viral replication." (PMID 39917304, 2025). "Our data suggest that the accessory components (RFC2, RFC3, RFC5, PCNA), polymerases (POLD1, POLD2, POLD3, POLE, POLE2, POLE4), and ligase LIG1, were downregulated during infection, for which the downregulation of RFC5, POLD1, POLD2, POLD3, POLE, and LIG1 was CagA-related." (PMID 33339161, 2020).
neurological diseases (1 paper, 2013). "Seven (12.7%) of the DEGs were associated with neurological diseases (BAT3, HS6ST1, IFI44L, RFC3, RPS9, STRC and TCF19) according to the IPA analysis (p = 0.003)." (PMID 23593218, 2013). "Remarkably, about 13% of the DEGs in FGF2 treated S252W fibroblasts were associated with neurological diseases (BAT3, HS6ST1, IFI44L, RFC3, RPS9, STRC and TCF19)." (PMID 23593218, 2013).
RFC3 also shares sentences with these, for which no sentence is quoted: ovarian tumor (2 papers); prostate carcinoma (2); adenoma (1); colon adenocarcinoma (1); diffuse large B-cell lymphoma (1); esophageal carcinoma (1); Kaposi's sarcoma (1); myxofibrosarcoma (1); nasopharyngeal carcinoma (1); pleomorphic liposarcoma (1); round cell liposarcoma (1); synovial sarcoma (1); thymoma (1); thyroid carcinoma (1).